A2M-AS1 (A2M antisense RNA 1)
Gene: Long non-coding RNA gene on chromosome 12 (9,065,163 to 9,068,689, forward strand). Ensembl gene ENSG00000245105.
Diseases named in the same sentence as A2M-AS1 in open-access papers:
A2M-AS1 is named in the same sentence as 2 diseases in open-access papers, as found by Europe PMC text mining. Sharing a sentence is not in itself a finding about the gene and the disease. The quoted sentences say what the papers report.
breast carcinoma (2 papers, 2022). "The function of A2M-AS1 as a positive regulatory factor to promote the metastasis of breast cancer has been characterized, and is related to a poor prognosis." (PMID 35783605, 2022). "For instance, A2M-AS1 has been reported to have regulatory effects on downstream factors such as CD2 and SELL, in the cell adhesion molecule pathway, indicating that A2M-AS1 may be a visible candidate prognostic factor and therapeutic target for breast cancer." (PMID 35237359, 2022).
infection (1 paper, 2025). The state of being infected such as from the introduction of a foreign agent such as serum, vaccine, antigenic substance or organism. "In order to investigate the functional role of A2M‐AS1 in PC, we stably overexpressed A2M‐AS1 in PANC‐1 cells with low levels via lentiviral infection and stably transduced BxPC‐3 cells with lentiviral shRNA constructs targeting A2M‐AS1, as confirmed by qRT‐PCR analysis." (PMID 40653606, 2025).